IMP3 (IMP U3 small nucleolar ribonucleoprotein 3)
Description:
Component of the 60-80S U3 small nucleolar ribonucleoprotein (U3 snoRNP). Required for the early cleavages during pre-18S ribosomal RNA processing. Part of the small subunit (SSU) processome, first precursor of the small eukaryotic ribosomal subunit. During the assembly of the SSU processome in the nucleolus, many ribosome biogenesis factors, an RNA chaperone and ribosomal proteins associate with the nascent pre-rRNA and work in concert to generate RNA folding, modifications, rearrangements and cleavage as well as targeted degradation of pre-ribosomal RNA by the RNA exosome.
Synonyms: C15orf12; MRPS4; FLJ10968; BRMS2
Tractability: Small molecule: a structure with a bound ligand is known. PROTAC: ubiquitination databases record sites on it; its protein half-life has been measured.
Gene: Protein-coding gene on chromosome 15 (75,639,085 to 75,648,706, reverse strand). Ensembl gene ENSG00000177971.
Subcellular location: Nucleus, nucleolus
Subcellular location (Human Protein Atlas): Nucleoli; Cytosol; Nucleoplasm
Pathways (Reactome):
Metabolism of RNA: Major pathway of rRNA processing in the nucleolus and cytosol; rRNA modification in the nucleus and cytosol
Gene Ontology:
Molecular function: protein binding; RNA binding; snoRNA binding; rRNA binding
Biological process: ribosomal small subunit biogenesis; maturation of SSU-rRNA; rRNA processing; ribosome biogenesis
Cellular component: Mpp10 complex; nucleolus; nucleus; preribosome; small-subunit processome; nucleoplasm
Genetic constraint (gnomAD): Loss-of-function variants: 17 observed, 9.96 expected, observed/expected ratio (o/e) 1.71, 90% interval 1.11 to 1.96. That is too few expected variants to judge how well the gene tolerates losing a copy. Missense variants: 290 observed, 262.88 expected, observed/expected ratio (o/e) 1.1, 90% interval 1 to 1.22. Synonymous variants: 167 observed, 120.19 expected, observed/expected ratio (o/e) 1.39, 90% interval 1.22 to 1.58.
Homologues: Orthologues: chimpanzee IMP3 (100% identical), macaque IMP3 (100% identical), pig IMP3 (99% identical), guinea pig IMP3 (98% identical), dog IMP3 (96% identical), mouse Imp3 (96% identical), zebrafish imp3 (68% identical), tropical clawed frog imp3 (68% identical), Drosophila melanogaster CG4866 (57% identical), Caenorhabditis elegans C48B6.2 (51% identical).
Diseases named in the same sentence as IMP3 in open-access papers:
IMP3 is named in the same sentence as 133 diseases in open-access papers, as found by Europe PMC text mining. Sharing a sentence is not in itself a finding about the gene and the disease. The quoted sentences say what the papers report.
breast carcinoma (14 papers, 2012 to 2025). "In this study, modification of cg25839482 for the IMP3 gene was first reported to be associated with breast cancer using two-sample MR combined with colocalization analysis." (PMID 34650928, 2021). "Prior studies in hepatocellular and breast cancers show that IGF2BP3 (IMP3) binds the 3′ UTR of SREBP1c mRNA, stabilizing the transcript and enhancing SREBP1c nuclear accumulation and transactivation of lipogenic targets, including FASN." (PMID 41614778, 2025). "The expression of IMP3 in CD44+CD24‐ESA+ cell clusters in breast cancer tissue was significantly upregulated." (PMID 38358034, 2024). "We finally identified the DNA methylation at cg2583948, which locates at the promoter region of IMP3 and inhibits IMP3 expression, as a crucial mediator between smoking and ER+ breast cancer." (PMID 34650928, 2021). "Further colocalization analysis showed that there was strong evidence (based on PPH4 > 0.8) supporting a common genetic causal SNP between the CpG site of cg2583948 [with IMP3 expression (PPH4 = 0.958)] and ER+ breast cancer." (PMID 34650928, 2021). "Downregulation of IMP3 in breast cancer cells led to increased sensitivity to doxorubicin and mitoxantrone by regulating the expression of breast-cancer resistance protein (BCRP)." (PMID 23965981, 2013). "IMP3, a member of the insulin-like growth factor II mRNA binding proteins (IMPs), is involved in the regulation of drug resistance in breast cancer." (PMID 23965981, 2013). "However, few studies focused on the relationship of IMP3 expression with other cancer types including breast cancer." (PMID 34650928, 2021). "Indeed, ubiquitin-mediated degradation of CCND3 by FBXL2 has been demonstrated in lung cancer, while in breast cancer cells, the RNA-binding protein IMP-3 can regulate CCND3 protein expression by directly binding to its mRNAs." (PMID 34440000, 2021). "Studies indicate that it could serve as a biomarker for basal-like breast carcinomas, and a recent report showed that the IMP3 is commonly overexpressed in ACCs of the breast." (PMID 30189404, 2018). "It had been reported that knockdown of IMP3 in cervical cancer, breast cancer and melanoma cell lines could reduce cell migration and invasiveness." (PMID 26837693, 2016). "Previous reports indicated that IMP3 expression could be regulated by growth factor signaling in breast cancer cells or miRNA in Drosophila." (PMID 23226335, 2012). "In breast cancer, IMP3 activates TAZ, a transcriptional co-activator of Hippo signaling that helps drive breast cancer stem cell function." (PMID 35366242, 2022). "In both oral squamous cell carcinoma and breast carcinoma cells, pharmacological inhibition of EGFR resulted in decreased expression of IMP3." (PMID 25886367, 2015). "The study included 118 patients with breast carcinoma diagnosed as TNBC and immunohistochemical staining for estrogen receptors (ER), progesterone receptors (PR), epidermal growth factor receptor 2 (HER2/neu), Ki-67, and IMP3 was performed." (PMID 32049813, 2020). "IMP3 is an mRNA-binding protein shown to be over-expressed in PDAC and various other malignancies including cervical, endometrial, bladder, lung, renal cell and breast carcinomas as well as glioblastoma and malignant melanoma." (PMID 25886367, 2015).
colorectal cancer (12 papers, 2013 to 2025). A primary or metastatic malignant neoplasm that affects the colon or rectum. "In cancer models, IMP3 KO mice demonstrated that IMP3 had a critical role in colorectal cancer (CRC) progression." (PMID 40141058, 2025). "Further research is needed to elucidate the precise mechanisms by which IMP3 contributes to lymphatic metastasis and to explore its potential as a therapeutic target or prognostic marker in colorectal cancer patients." (PMID 39328205, 2024). "One study focused on colorectal cancer reported that IMP3 directly regulates MEKK1 mRNA, and thus activates the MEK/ERK pathway." (PMID 36740684, 2023). "IMP3 is highly expressed in colorectal cancer (CRC) tissue, where its expression often correlates with poor prognosis." (PMID 37024466, 2023). "Two recent studies have suggested that IMP3 regulates the progression of colorectal cancer by activation of MEKK1/ERK pathway and subsequent interaction with ELAVL1." (PMID 37024466, 2023). "The mammalian paralogue of Imp, IMP-3, prevents cell death after misexpression in lymphoblast cells, and inhibits apoptosis in human colorectal cancer cells." (PMID 38031099, 2023). "Overexpression of IMP3 was found in colorectal cancer tissue, and downregulation of IMP3 suppressed the protein translation rates and cell growth in colorectal cancer cells." (PMID 34650928, 2021). "As a prognostic marker, different studies demonstrated that IMP3 can identify subgroups of patients affected by localized renal cell carcinomas, superficial urothelial carcinomas, and colorectal carcinomas with poorer prognosis." (PMID 25695077, 2015). "IMP3 was identified as an independent prognostic factor in colorectal cancer (HR, 0.618; 95% CI, 0.394–0.972; Wald χ2=4.343; P=0.037)." (PMID 24137402, 2013). "The correlation between IMP3 expression and the clinicopathological features of colorectal cancer was evaluated by the χ2 and Fisher’s exact tests." (PMID 24137402, 2013). "To see if the effect of IMP3 on the stress-induced ligands ULBP2 is specific for the colon carcinoma RKO cell line, we performed a knockdown of IMP3 in the colorectal carcinoma HCT116 and in the embryonic kidney-derived cell line 293T and verified the knockdowns using WB." (PMID 26982091, 2016). "In HCT116 colorectal carcinoma cell lines, the knockdown resulted in a significant increase of ULBP2 of more than 30%; similarly, we observed an increase of about 15% for ULBP2 in 293T upon IMP3 loss this cell line." (PMID 26982091, 2016). "In colorectal cancer, IMP3 is typically overexpressed rather than mutated." (PMID 39328205, 2024). "The authors suggest that inhibiting IMP3, possibly in combination with a MEK1 inhibitor, may provide new potential therapeutic strategies for colorectal cancer treatment." (PMID 36740684, 2023). "A study has shown that IMP3 directly binds to the 3′-UTR of MEKK1 mRNA, thereby regulating its stability, promoting MEKK1 expression, and subsequently activating the MEK1/ERK signaling pathway, ultimately facilitating the malignant biological processes of colorectal cancer cells." (PMID 39328205, 2024).
lymph node metastasis (9 papers, 2014 to 2024). "The Spearman correlation test revealed a robust linear association between IMP3 expression and both lymph node metastasis (p = 0.004) and TNM stage (p = 0.005)." (PMID 39328205, 2024). "The results showed that IMP3 expression was significantly associated with tumor size, differentiation, lymph node metastasis and the clinical stage of NSCLC (P=0.013, P<0.001, P=0.004 and P<0.001, respectively)." (PMID 25789070, 2015). "Several studies have reported a correlation between IMP3 expression and lymph node metastasis in various cancers." (PMID 39328205, 2024). "In oral squamous cell carcinoma (oSCC), high IMP3 expression correlates with lymph node metastasis (N+) and decreased 5-year survival." (PMID 37627115, 2023). "In this study, the tumour marker IMP3 showed clear correlations with aggressiveness features (lymph node metastases, local recurrences, and progression-free survival)." (PMID 37627115, 2023). "In summary, IMP3 appears to play a multifaceted role in lymphatic metastasis by promoting cancer cell behaviors conducive to metastasis, potentially influencing lymphangiogenesis, and correlating with lymph node metastasis." (PMID 39328205, 2024). "We demonstrated, for the first time, the possible role of IMP3 overexpression on disease-free survival in LSCC patients and its elevated expression in cases with lymph node metastases." (PMID 34503117, 2021). "All thirteen adult cases with lymph node metastasis based on histological and/or radiological findings showed at least focal and weak IMP3 positivity in epithelial components, while 10/16 cases without metastasis showed IMP3 expression (one case was not available for analysis)." (PMID 32144540, 2020).
renal cell carcinoma (9 papers, 2010 to 2024). "Survival analyses have indicated that IMP3 expression is negatively linked to a favorable prognosis for gastric adenocarcinoma, renal cell carcinoma and hepatocellular carcinoma." (PMID 24137402, 2013). "Moreover, in a recent paper, Tschirdewahn and colleagues found that serum IMP3 levels associated with poor survival in renal cell carcinoma (RCC) patients, thus suggesting its role as a biomarker to improve the risk-stratification of RCC patients and to optimise therapeutic and follow-up decisions." (PMID 37024466, 2023). "In renal cell carcinoma, IMP3 can also promote cell migration and invasion by activation of NF-κB pathway." (PMID 26837693, 2016). "IMP3 is a prognostic biomarker in patients with endometrial serous carcinoma and renal cell carcinoma." (PMID 25295085, 2014). "IMP3 has been shown to be overexpressed in testicular cancer, renal cell carcinoma, ovarian carcinoma, gastric cancer, colon cancer and adenocarcinoma of the lung." (PMID 25295085, 2014). "A simulated TMA with between 1 and 10 cores was designed to study tumor expression of 6 biomarkers with varied expression patterns (B7-H1, B7-H3, survivin, Ki-67, CAIX, and IMP3) using 100 patients with clear cell renal cell carcinoma (RCC)." (PMID 20609235, 2010). "However, expression of IMP3 could be observed in several kinds of cancer like in colon carcinoma, adenocarcinomas, urothelial carcinomas, lymphomas or renal cell carcinomas." (PMID 26982091, 2016).
cervical carcinoma (7 papers, 2015 to 2025). A carcinoma arising from either the exocervical squamous epithelium or the endocervical glandular epithelium. "We therefore propose that IMP3 biases cervical cancer cells toward a lipid-addicted state, whereas IMP3 loss shifts cells toward a mitotic-checkpoint–enriched state operating under metabolic constraint." (PMID 41614778, 2025). "Collectively, our findings chart a fresh paradigm, offering promising therapeutic avenues for cervical cancer management, with an emphasis on targeting IMP3 and its associated metabolic accomplices." (PMID 41614778, 2025). "Loss-of-function experiments indicate that IMP3 is involved in the regulation of proliferation, motility, and invasion of leukemic, cervical carcinoma, glioblastoma, and oral carcinoma cells." (PMID 25886367, 2015). "A previous study showed that expression of insulin-like growth factor II messenger RNA (mRNA)-binding protein 3 (IMP3) is associated with poor prognosis in cervical cancer." (PMID 26624896, 2015). "Together, this multi-layer framework links IMP3 to coordinated changes in respiration and lipid metabolism, delineates gene networks that accompany these shifts in patient tissues, and highlights metabolite-associated proteins as potential therapeutic entry points in cervical cancer." (PMID 41614778, 2025). "We note that our mechanistic studies were performed in HeLa cells; validation in primary cervical cancer cells and patient-derived models will be essential to generalize IMP3’s impact on lipid metabolism and clinical outcome." (PMID 41614778, 2025). "Together, these data identify IMP3 as a regulator of energy and lipid metabolism in cervical cancer and support its evaluation as a biomarker and potential therapeutic target." (PMID 41614778, 2025). "Concurrently, we employed advanced bioinformatics techniques to discern the potential implications of IMP3 overexpression in cervical cancer progression." (PMID 41614778, 2025). "Complementary bioinformatic analyses of Gene Expression Omnibus datasets revealed that cervical cancers with high IMP3 expression exhibit coordinated deregulation of metabolic, cell-cycle, and inflammatory response pathways relative to normal cervical tissue." (PMID 41614778, 2025). "Together, our results suggest that circCDKN2B-AS1 cooperates with IMP3 to promote glycolysis of cervical cancer cells." (PMID 33308298, 2020). "Overexpression of IMP3 is observed in a series of human malignancies, including ovarian, endometrial, and cervical cancers." (PMID 27733814, 2016). "Previous studies have shown that IMP3 is crucial for maintaining the invasive phenotype of cervical carcinoma, oral squamous cell carcinoma, hepatocellular carcinoma, and glioblastoma cells." (PMID 25886367, 2015). "Multiple lines of evidence support a clinically relevant role for IMP3 in cervical cancer." (PMID 41614778, 2025). "Here, we test the hypothesis that IMP3 regulates mitochondrial function and lipid metabolic programs in cervical cancer." (PMID 41614778, 2025). "Then, we detected the glycolysis capabilities of IIP-treated cells and found that glycolysis in SiHa and CaSki cells treated with IIP was also decreased, suggesting that IIP represses glycolysis by blocking the interaction between circCDKN2B-AS1 and the IMP3 protein in cervical cancer cells." (PMID 33308298, 2020). "Thus, our results suggest that circCDKN2B-AS1 facilitates aerobic glycolysis and the progression of cervical cancer via interacting with IMP3 and HK2 mRNA in vivo." (PMID 33308298, 2020). "Since both IMP3 and TPX2 have been associated with growth of cervical cancer, we speculated that they might also be associated with growth of CIN." (PMID 26624896, 2015). "Intriguingly, this upsurge in IMP3 might be intricately intertwined with the modulation of metabolic pathways, cell cycle progression, and inflammatory responses, all converging to potentially foster the tumorigenesis trajectory in cervical cancer." (PMID 41614778, 2025).
cervical carcinoma (continued). "Interestingly, these associations were predominantly negative, indicating that higher IMP3 expression is linked to lower expression of these hub genes in cervical cancer." (PMID 41614778, 2025). "Thus, we hypothesized that circCDKN2B-AS1 stabilizes HK2 mRNA and facilitates aerobic glycolysis in cervical cancer by recruiting the IMP3 protein to the 3’UTR of HK2 mRNA." (PMID 33308298, 2020). "These orthogonal readouts support a model in which IMP3 sustains lipogenic transcription by enhancing SREBF1 mRNA output, thereby promoting lipid accumulation and membrane remodeling in cervical cancer cells." (PMID 41614778, 2025). "Future studies should aim to dissect the functional interplay between IMP3 and IDH1, thereby elucidating its role in mitochondrial metabolic regulation and its broader implications for cervical cancer initiation and progression." (PMID 41614778, 2025). "Together, these findings support a model in which IMP3 functions upstream of the SREBP–FASN axis as an mRNA-binding amplifier of lipogenic signaling, promoting lipid accumulation in cervical cancer cells and suggesting a tractable metabolic vulnerability." (PMID 41614778, 2025). "Utilization of an inhibitory peptide to block the interaction between circCDKN2B-AS1 and the IMP3 protein impeded the binding of IMP3 to the 3’UTR of HK2 mRNA and suppressed aerobic glycolysis in cervical cancer cells." (PMID 33308298, 2020). "We further identified that circCDKN2B-AS1 facilitates aerobic glycolysis by interacting with the IMP3 protein to stabilize HK2 mRNA, consequently promoting the malignant phenotype in cervical cancer cells." (PMID 33308298, 2020). "The expression level of circCDKN2B-AS1 fated the binding of IMP3 to the 3′ untranslated region (UTR) of HK2 mRNA, consequently affecting the malignant cell phenotype and aerobic glycolysis in cervical cancer in vitro and in vivo." (PMID 33308298, 2020). "In addition, IMP3 was upregulated in HPV16-positive cervical cancer and precancerous tissues compared with normal tissues and facilitated aerobic glycolysis by stabilizing HK2 mRNA, consequently promoting the malignant phenotype in cervical cancer cells." (PMID 35706003, 2022). "Our findings demonstrate that circCDKN2B-AS1 facilitates aerobic glycolysis by sponging the IMP3 protein to stabilize HK2 mRNA, consequently promoting the malignant phenotype in cervical cancer, which may provide a potential approach for cervical cancer therapeutics." (PMID 33308298, 2020).